H2BC5 (H2B clustered histone 5)
Description:
Core component of nucleosome. Nucleosomes wrap and compact DNA into chromatin, limiting DNA accessibility to the cellular machineries which require DNA as a template. Histones thereby play a central role in transcription regulation, DNA repair, DNA replication and chromosomal stability. DNA accessibility is regulated via a complex set of post-translational modifications of histones, also called histone code, and nucleosome remodeling.
Synonyms: H2B/b; H2BFB; HIRIP2; HIST1H2BD; H2B.1B; H2B/a; H2B/g; H2B/h; H2B/k; H2B/l; H2BFA; H2BFG; H2BFH; H2BFK; H2BFL; HIST1H2BC; HIST1H2BE; HIST1H2BF; HIST1H2BG; HIST1H2BI; and 1 more
Tractability: Small molecule: a structure with a bound ligand is known. PROTAC: UniProt records ubiquitination sites on it; ubiquitination databases record sites on it.
Gene: Protein-coding gene on chromosome 6 (26,158,122 to 26,171,349, forward strand). Ensembl gene ENSG00000158373.
Subcellular location: Nucleus; Chromosome
Subcellular location (Human Protein Atlas): Nucleoplasm; Cytosol
Pathways (Reactome):
Gene expression (Transcription): B-WICH complex positively regulates rRNA expression; DNA methylation; ERCC6 (CSB) and EHMT2 (G9a) positively regulate rRNA expression; MLL4 and MLL3 complexes regulate expression of PPARG target genes in adipogenesis and hepatic steatosis; NoRC negatively regulates rRNA expression; PRC2 methylates histones and DNA; RNA Polymerase I Promoter Escape; RNA Polymerase I Promoter Opening; RUNX1 regulates genes involved in megakaryocyte differentiation and platelet function; RUNX1 regulates transcription of genes involved in differentiation of HSCs; Regulation of endogenous retroelements by KRAB-ZFP proteins; Regulation of endogenous retroelements by Piwi-interacting RNAs (piRNAs); Regulation of endogenous retroelements by the Human Silencing Hub (HUSH) complex; SIRT1 negatively regulates rRNA expression; Transcriptional regulation by small RNAs
Chromatin organization: CHD1 and CHD2 subfamily; CHD6, CHD7, CHD8, CHD9 subfamily; ChAHP complex assembly; HATs acetylate histones; HDACs deacetylate histones; Interaction of NuRD complexes with transcription factors; NuRD complex assembly
DNA Repair: Cleavage of the damaged purine; Cleavage of the damaged pyrimidine; Nonhomologous End-Joining (NHEJ); Processing of DNA double-strand break ends; Recognition and association of DNA glycosylase with site containing an affected purine; Recognition and association of DNA glycosylase with site containing an affected pyrimidine; Recruitment and ATM-mediated phosphorylation of repair and signaling proteins at DNA double strand breaks
Cell Cycle: Condensation of Prophase Chromosomes; Deposition of new CENPA-containing nucleosomes at the centromere; G2/M DNA damage checkpoint; Inhibition of DNA recombination at telomere; Packaging Of Telomere Ends
Developmental Biology: Activation of anterior HOX genes in hindbrain development during early embryogenesis; Chromatin modifications during the maternal to zygotic transition (MZT); Replacement of protamines by nucleosomes in the male pronucleus; Transcriptional regulation of granulopoiesis
Disease: Defective pyroptosis; Dengue Virus-Host Interactions
and 18 more pathways
Gene Ontology:
Molecular function: protein binding; DNA binding; structural constituent of chromatin; protein heterodimerization activity
Biological process: antibacterial humoral response; antimicrobial humoral immune response mediated by antimicrobial peptide; chromatin organization; innate immune response in mucosa
Cellular component: extracellular exosome; nucleus; nucleoplasm; nucleosome; chromosome
Genetic constraint (gnomAD): Loss-of-function variants: 9 observed, 6.03 expected, observed/expected ratio (o/e) 1.49, 90% interval 0.86 to 1.93. That is too few expected variants to judge how well the gene tolerates losing a copy. Missense variants: 175 observed, 174.67 expected, observed/expected ratio (o/e) 1, 90% interval 0.88 to 1.14. Synonymous variants: 133 observed, 74.14 expected, observed/expected ratio (o/e) 1.79, 90% interval 1.55 to 1.97.
Homologues: Orthologues: chimpanzee H2BC5 (100% identical), macaque H2BC5 (100% identical), mouse H2bc14 (100% identical), pig H2BC5 (100% identical), rat Hist1h2bo (98% identical). Paralogues in human: H2BC10 (99% identical), H2BC15 (99% identical), H2BC4 (99% identical), H2BC6 (99% identical), H2BC7 (99% identical), H2BC8 (99% identical), H2BC12 (98% identical), H2BC21 (98% identical), H2BC9 (98% identical), H2BC11 (98% identical), H2BC13 (98% identical), H2BC17 (98% identical), and 9 more.
Diseases named in the same sentence as H2BC5 in open-access papers:
H2BC5 is named in the same sentence as 24 diseases in open-access papers, as found by Europe PMC text mining. Sharing a sentence is not in itself a finding about the gene and the disease. The quoted sentences say what the papers report.
cervical cancer (3 papers, 2017 to 2022). A primary or metastatic malignant neoplasm involving the cervix. "Several studies have shown that H2BC5, H2BC9, and H2BC11 are independent prognostic factors of cervical cancer, and H2BC12 is an independent prognostic factor for low-grade glioma." (PMID 36387186, 2022).
glioma (2 papers, 2022 to 2023). A benign or malignant brain and spinal cord tumor that arises from glial cells (astrocytes, oligodendrocytes, ependymal cells). "Both univariate and multivariate regression analysis indicated that H2BC5, H2BC9, H2BC11, H2BC21 were risk factors for overall survival of glioma patients, and had a similar impact as WHO grade, IDH status, and age." (PMID 36387186, 2022). "Univariate and multivariate Cox analysis showed that H2BC5, H2BC9, H2BC11, and H2BC21 are high-risk factors for glioma." (PMID 36387186, 2022). "In particular, high H2BC5, H2BC9, H2BC11, and H2BC21 expression was associated with poor glioma prognosis." (PMID 36387186, 2022). "Kaplan-Meier survival analysis showed that high expression of H2BC5, H2BC9, H2BC11, and H2BC21 correlated with a poor OS, DFS, and PFI of glioma patients." (PMID 36387186, 2022). "Enrichment analysis of H2BC5, H2BC9, H2BC11, and H2BC21 was also conducted to understand how the H2B gene is involved in the pathological progression of glioma." (PMID 36387186, 2022). "The methylation status of H2BC5, H2BC9, H2BC11, and H2BC21 in different glioma cohorts was evaluated in the Methsurv database." (PMID 36387186, 2022). "Expression of H2BC5, H2BC9, H2BC11, and H2BC21 was higher in glioma tissues." (PMID 36387186, 2022). "Collectively, these data indicated that H2BC5, H2BC9, H2BC11, and H2BC21 could independently predict glioma prognosis." (PMID 36387186, 2022). "H2B family genes, especially H2BC5 and H2BC9, as molecular biomarkers, have high specificity and sensitivity for the prognosis of glioma patients, and are significantly correlated with glioma grade, age and other factors, showing a high research potential." (PMID 36387186, 2022). "In summary, H2BC5, H2BC9, H2BC11, and H2BC21 were independent prognostic indicators of glioma, and H2BC9 and H2BC11 may correlate with tumor immunity." (PMID 36387186, 2022). "The analysis of H2B family gene expression in glioma showed that H2BC5, H2BC9, H2BC11, and H2BC21 can be used as independent predictive factors for glioma prognosis, and overexpression of H2BC9 and H2BC11 may lead to tumor deterioration through the immune system." (PMID 36387186, 2022). "Moreover, the ROC curve showed that H2BC5, H2BC9, H2BC11, and H2BC21 all had meaningful predictive power for glioma, especially H2BC9 and H2BC11, which showed excellent sensitivity and specificity in predicting the survival of glioma patients, with an area under the curve (AUC) of >0.8." (PMID 36387186, 2022).
astrocytoma (1 paper, 2022). "The GSE4271 and GSE4412 datasets were used as a supplement to the results and suggested the prognostic value of H2BC5, H2BC9, H2BC21 on astrocytoma." (PMID 36387186, 2022).
cholangiocarcinoma (1 paper, 2024). A carcinoma that arises from the intrahepatic biliary tree (intrahepatic cholangiocarcinoma) or from the junction, or adjacent to the junction, of the right and left hepatic ducts (hilar cholangiocarcinoma). "H2BC5 is a member of the H2B histone family usually upregulated in cholangiocarcinoma and esophageal carcinoma, among many others." (PMID 39285481, 2024).
embryonic carcinoma (1 paper, 2022). "However, H2BC5 and H2BC12 were found to be hypermethylated in malignant pluripotent embryonic carcinoma, and H2BC12 was also shown to be hypermethylated in neuroblastomas." (PMID 36387186, 2022).
lung adenocarcinoma (1 paper, 2024). A carcinoma that arises from the lung and is characterized by the presence of malignant glandular epithelial cells. "Bioinformatic analyses have shown that H2BC5 is more highly expressed in lung adenocarcinoma and squamous cell carcinoma tissues compared to healthy tissue, with high expression correlating with better survival in lung cancer patients." (PMID 39766770, 2024).
psoriasis (1 paper, 2025). An autoimmune condition characterized by red, well-delineated plaques with silvery scales that are usually on the extensor surfaces and scalp. "In the CD group, the AUC of diagnostic genes H2BC5 and AQP9 were 61.333% and 93.909%, in the psoriasis group, the AUC of IL1R2, AQP9, ZNF14 and H2BC5 were 75.641%, 82.906%, 93.162%, and 51.709%." (PMID 40093802, 2025). "The same ROC analysis was also performed in the psoriasis group, and the AUC of IL1R2, AQP9, ZNF14 and H2BC5 were obtained to be 78.728%, 78.698%, 92.194% and 80.562%." (PMID 40093802, 2025).
cancer (6 papers, 2014 to 2024). A tumor composed of atypical neoplastic, often pleomorphic cells that invade other tissues. "Upregulation of NUPR1 and H2BC5 genes has been associated with various cancer types." (PMID 39285481, 2024).
H2BC5 also shares sentences with these, for which no sentence is quoted: Alcoholism (2 papers); breast carcinoma (2); systemic lupus erythematosus (2); tumor (2); acute myeloid leukemia (1); cervical squamous cell carcinoma (1); COVID-19 (1); esophageal carcinoma (1); gastric cancer (1); infection (1); lung carcinoma (1); migraine (1); myeloma (1); neuroblastoma (1); prostate carcinoma (1); squamous cell carcinoma (1).